DERL2 (derlin 2)
Description:
Functional component of endoplasmic reticulum-associated degradation (ERAD) for misfolded lumenal glycoproteins, but not that of misfolded nonglycoproteins. May act by forming a channel that allows the retrotranslocation of misfolded glycoproteins into the cytosol where they are ubiquitinated and degraded by the proteasome. May mediate the interaction between VCP and misfolded glycoproteins. May also be involved in endoplasmic reticulum stress-induced pre-emptive quality control, a mechanism that selectively attenuates the translocation of newly synthesized proteins into the endoplasmic reticulum and reroutes them to the cytosol for proteasomal degradation. (Microbial infection) In contrast to DERL1, it is not involved in the degradation of MHC class I heavy chains following infection by cytomegaloviruses.
Synonyms: DERtrin-2; FLANA; CGI-101; F-LAN-1; F-LANa; derlin-2
Tractability: Antibody: UniProt predicts a signal peptide or a membrane-spanning region. PROTAC: ubiquitination databases record sites on it.
Gene: Protein-coding gene on chromosome 17 (5,471,254 to 5,486,811, reverse strand). Ensembl gene ENSG00000072849.
Subcellular location: Endoplasmic reticulum membrane
Subcellular location (Human Protein Atlas): Endoplasmic reticulum
Pathways (Reactome):
Disease: Defective CFTR causes cystic fibrosis; Hh mutants are degraded by ERAD
Immune System: AMPK-induced ERAD and lysosome mediated degradation of PD-L1(CD274)
Metabolism of proteins: ER Quality Control Compartment (ERQC)
Signal Transduction: Hedgehog ligand biogenesis
Transport of small molecules: ABC-family protein mediated transport
Gene Ontology:
Molecular function: protein binding; protein-containing complex binding; signal recognition particle binding
Biological process: endoplasmic reticulum unfolded protein response; ERAD pathway; negative regulation of retrograde protein transport, ER to cytosol; positive regulation of cell growth; positive regulation of cell population proliferation; retrograde protein transport, ER to cytosol; ubiquitin-dependent protein catabolic process
Cellular component: endoplasmic reticulum; endoplasmic reticulum membrane; membrane; early endosome; late endosome
Genetic constraint (gnomAD): Loss-of-function variants: 6 observed, 14.79 expected, observed/expected ratio (o/e) 0.41, 90% interval 0.22 to 0.8. The upper end of that interval is the gene's LOEUF score, 0.8, which puts it in group 3 of 6, group 1 being the genes least tolerant of losing a copy. Missense variants: 148 observed, 200.07 expected, observed/expected ratio (o/e) 0.74, 90% interval 0.65 to 0.85. Synonymous variants: 86 observed, 78.92 expected, observed/expected ratio (o/e) 1.09, 90% interval 0.91 to 1.3.
Homologues: Orthologues: chimpanzee DERL2 (100% identical), pig DERL2 (100% identical), rabbit DERL2 (100% identical), guinea pig DERL2 (99% identical), dog DERL2 (99% identical), macaque DERL2 (99% identical), mouse Derl2 (99% identical), rat Derl2 (99% identical), tropical clawed frog derl2 (92% identical), Caenorhabditis elegans der-2 (64% identical), Drosophila melanogaster Der-2 (62% identical). Paralogues in human: DERL3 (74% identical), DERL1 (35% identical).
Diseases named in the same sentence as DERL2 in open-access papers:
DERL2 is named in the same sentence as 23 diseases in open-access papers, as found by Europe PMC text mining. Sharing a sentence is not in itself a finding about the gene and the disease. The quoted sentences say what the papers report.
Brain atrophy (3 papers, 2021 to 2022). Partial or complete wasting (loss) of brain tissue that was once present. "Both Derlin-1- and Derlin-2-deficient mice exhibited widespread postnatal brain atrophy, which was particularly severe in the cerebellum and striatum." (PMID 34355142, 2021). "Although we cannot exclude the possibility that brain atrophy depends on body growth inhibition, there might be another mechanism by which CNS-specific Derlin-1 or Derlin-2 deficiency induces brain atrophy." (PMID 34355142, 2021).
chronic lymphocytic leukemia (2 papers, 2022 to 2024). "In chronic lymphocytic leukemia, preclinical and clinical evidence has shown the amplification of DERL2 mRNA levels." (PMID 37815698, 2024). "Notably, a previous investigation in chronic lymphocytic leukemia mice examined the distinct expression patterns of DERL2 in cancerous tissues and cells." (PMID 37815698, 2024).
glioma (2 papers, 2021 to 2025). A benign or malignant brain and spinal cord tumor that arises from glial cells (astrocytes, oligodendrocytes, ependymal cells). "Here, we identified a novel ER stress and UPR-driven gene signature, ESURATAG, composed of six genes (DERL2, RPN2, SEC13, SEC61A1, SEC61B, and STT3A) that are significantly upregulated in gliomas from older patients and strongly linked to tumor aggressiveness." (PMID 40718795, 2025). "Six out of eight genes namely, DERL2, RPN2, SEC13, SEC61A1, SEC61B and STT3A were interacting, and were combined into ER stress and UPR-driven aging-related tumor aggressiveness in glioma (ESURATAG) gene signature." (PMID 40718795, 2025). "In the PPI network of OS9, OS9 and derlin 2 (DERL2) involve in protein processing in the endoplasmic reticulum and complicate CFTR (Cystic fibrosis transmembrane conductance regulator) causes cystic fibrosis pathways, which may be associated with the prognosis of glioma with mutant PTEN." (PMID 34336645, 2021). "Protein expression of genes in our ESURATAG-GS was also significantly upregulated in primary tumors compared to normal tissues in glioma patients (protein expression data for DERL2 was not available)." (PMID 40718795, 2025). "We identified ER stress and UPR as key aging-related mechanism behind tumor aggressiveness in gliomas, and developed a six gene “ER Stress and UPR-driven Aging-related Tumor Aggressiveness in Glioma” (ESURATAG) gene signature, comprising DERL2, RPN2, SEC13, SEC61A1, SEC61B, and STT3A." (PMID 40718795, 2025).
neuropathy (2 papers, 2019 to 2024). A disorder affecting the nervous system that manifests with pain, tingling, numbness, and/or muscle weakness. "Deletion of Derlin-2 from S63del Schwann cells exacerbates both the early and late features of the neuropathy, indicating that ERAD is protective, most likely because of its role in degrading the misfolded P0-S63del protein, as our in vitro data suggest." (PMID 30995221, 2019). "Here we show that absence of Derlin-2 dramatically exacerbates the S63del-CMT1B neuropathy, pointing at the enhancement of ERAD as a potential strategy to treat the disease." (PMID 30995221, 2019). "Moreover, we provide strong evidence that the Schwann cell-specific ablation of the ERAD factor Derlin-2 in S63del nerves exacerbates both the myelin defects and the UPR in vivo, unveiling a protective role for ERAD in CMT1B neuropathy." (PMID 30995221, 2019). "Altogether these data indicate that Derlin-2 is neither required for normal developmental myelination nor for remyelination after injury, but it appears to be protective in early stages of the CMT1B neuropathy." (PMID 30995221, 2019).
cholangiocarcinoma (1 paper, 2024). A carcinoma that arises from the intrahepatic biliary tree (intrahepatic cholangiocarcinoma) or from the junction, or adjacent to the junction, of the right and left hepatic ducts (hilar cholangiocarcinoma). "DERL2 (derlin 2) is a critical component of the endoplasmic reticulum quality control pathway system whose mutations play an important role in carcinogenesis, including cholangiocarcinoma (CHOL)." (PMID 37815698, 2024).
colorectal cancer (1 paper, 2014). A primary or metastatic malignant neoplasm that affects the colon or rectum. "DERL1 and DERL2 5′-end CpG island were unmethylated in all cases, but DERL3 CpG island promoter hypermethylation was found in four colorectal cancer cell lines: HCT-116, HCT-15, COLO-205 and SW48." (PMID 24699711, 2014).
diabetes (1 paper, 2015). "Thus Derlin-2, HRD1 and p97 represent potentially interesting new drug targets, opening new avenues for the treatment and possibly also the prevention of auto-immune diabetes." (PMID 26107514, 2015).
hepatocellular carcinoma (1 paper, 2023). A malignant tumor that arises from hepatocytes. "In conclusion, the inhibitory effect of FAM134B on hepatocellular carcinoma (HCC) cell autophagy is attributed to its suppression of endoplasmic reticulum stress‐related degradation factors, including DERL2, EDEM1, SEL1L and HRD1." (PMID 37728036, 2023).
Insulin resistance (1 paper, 2012). Increased resistance towards insulin, that is, diminished effectiveness of insulin in reducing blood glucose levels. "In this study, increased abundance of Sec24a, glutathione S-transferase, and derlin-2 may suggest that ER stress contribute to the insulin resistance in the high fat fed mice." (PMID 33907358, 2012).
liver cancer (1 paper, 2023). An epithelial or non-epithelial malignant neoplasm that arises from the liver. "FAM134B inhibits HCC cell autophagy and promotes the progression of liver cancer by inhibiting the expression of ER stress‐related degradation factors such as DERL2, EDEM1, SEL1L and HRD1." (PMID 37728036, 2023). "The results exhibited varying degrees of upregulation in the expression of DERL2, EDEM1, SEL1L and HRD1 in Hep3B cells of the sh‐FAM134B group when compared to the sh‐NC group (p < 0.05), indicating the effective induction of ER stress in Hep3B liver cancer cells by sh‐FAM134B." (PMID 37728036, 2023).
tumor (4 papers, 2021 to 2025). "Consistent with the in vitro findings, mice transplanted with DERL2-deficient QBC939 cells exhibited a substantial decrease in tumor weight and size, providing further evidence of the crucial role played by DERL2 in CHOL tumorigenesis." (PMID 37815698, 2024). "Subsequent bioinformatics analysis was performed to elucidate the pan-cancer expression landscape of DERL2, as the availability of normal tissues and paired tumor tissues was limited for differential expression analysis across various cancers." (PMID 37815698, 2024). "Utilizing the TCGA pan-cancer cohort’s normal/tumor data, we observed the prevalence of DERL2 mRNA expression across a wide range of cancer types, including CHOL." (PMID 37815698, 2024). "The results also showed that the highly expressed DERL2 might favor the tumor immune infiltrates of CHOL cells." (PMID 37815698, 2024). "DERL2 ectopically expressed in CHOL cells promoted cell proliferation and colony formation rates, and depleting DERL2 in CHOL cells curbed tumor growth in vitro and in vivo." (PMID 37815698, 2024).
cancer (2 papers, 2014 to 2024). A tumor composed of atypical neoplastic, often pleomorphic cells that invade other tissues. "In the present study, we made novel observations regarding the differential expression of DERL2 mRNA across various cancer types, accompanied by the presence of DERL2 mutants in different cancers." (PMID 37815698, 2024). "Consistently, a comparison of DERL2 expression in TCGA tumors and normal tissues revealed elevated mRNA levels of DERL2 in pan-cancer samples." (PMID 37815698, 2024). "DERL1, DERL2 and DERL3 are gene candidates for hypermethylation-associated inactivation in human cancer because a 5′-CpG island is located around their transcription start sites." (PMID 24699711, 2014). "In our current investigation, we have discovered that DERL2 functions to stabilize BAG6, potentially contributing to cancer progression." (PMID 37815698, 2024).
skeletal dysplasia (2 papers, 2024 to 2025). Any Mendelian diseases that affects growth and development of the skeleton. "Global knockout of DERL2 results in perinatal lethality, and the few surviving mice exhibit skeletal dysplasia due to defective collagen secretion in costal chondrocytes." (PMID 40414938, 2025).
neurodegenerative disease (1 paper, 2021). A disorder of the central nervous system characterized by gradual and progressive loss of neural tissue and neurologic function. "Although further investigation is necessary to clarify the precise mechanisms by which Derlin-1 and Derlin-2 regulate SREBP-2 activation, we propose that Derlins may be a therapeutic target to ameliorate or delay the progression of neurodegenerative diseases." (PMID 34355142, 2021).
DERL2 also shares sentences with these, for which no sentence is quoted: acute coronary syndrome (1 paper); asthenozoospermia (1); Azoospermia (1); cystic fibrosis (1); heart failure (1); infection (1); Infertility (1); microcephaly (1); neurological disorders (1).